SRSF1 (serine and arginine rich splicing factor 1)
Diseases named in the same sentence as SRSF1 in open-access papers (continued):
Sharing a sentence is not in itself a finding about the gene and the disease.
cancer (continued). "The ability of Myc to regulate SRSF1 and of WT1 to regulate SRPK1 expression is particularly interesting as these two transcription factors are associated with a wide range of cancers." (PMID 24101931, 2013). "We and others have previously reported that MALAT1-depleted cancer cells show increased levels (including the dephosphorylated pool) of SRSF1." (PMID 23555285, 2013). "Secondly, SRSF1 gene transcription is activated by the prooncogenic transcription factor Myc which is itself activated in some cancers." (PMID 23935626, 2013). "Beside the already mentioned SAM68, one likely candidate is SRSF1, a splicing factor that is upregulated in many human cancers and was shown to behave as an oncogene in mice and humans." (PMID 23983695, 2013). "The mechanism of SRSF1 upregulation in cancer cells has been explained at a mechanistic level, and the effects of this upregulation in terms of gene expression control have been mapped onto the pathway of oncogenesis." (PMID 23935626, 2013). "SRSF1 has been shown to enhance transformation in some cancers; therefore, the increase in the level of SRSF1 should occur earlier than the morphological or immunological change." (PMID 22839530, 2012). "The key findings from this study highlight the importance of the cellular context of different cancer cells for the function of multifunctional RBPs like SRSF1 and have implications for therapeutic approaches employed to target Mcl-1." (PMID 23284704, 2012). "The splicing factor SRSF1 and antiapoptotic protein Mcl-1, including its isoforms Mcl-1L and Mcl-1S, play significant roles in cancer development; however, the regulatory mechanisms of the SRSF1-Mcl-1 axis in GC remain unclear." (PMID 42293332, 2026). "Although much of the literature on SRSF1 focuses on its role in cancer, its regulatory functions in apoptosis and cell proliferation suggest it may influence immune response and mammary gland health in cattle." (PMID 41252605, 2025). "SRSF1 proteins belong to an important splicing factor (SF) family and bind to different splicing regulatory elements (SREs) to promote or inhibit splicing, such as oncogenic splice-switching of PTpMT1, which promoting the progression of cancer." (PMID 40176901, 2025). "Among the top downregulated 50 genes, there were other cancer relevant genes such as cell cycle associated (CCNF1, CCNB1, ZWINT), cancer signaling (STK32B, IGF1, FLT1) and splicing associated (HNRNPM, HNRNPU, SRSF1) genes, which are active areas to investigate further." (PMID 38200580, 2024). "Furthermore, SRSF1 levels are elevated in many different cancers, and it is considered a proto-oncogene." (PMID 36759613, 2023). "In order to test whether SRSF1 is dispensable for the survival of cancer cells, we extracted the cancer dependency score of SRSF1 from a genome-wide CRISPR screening database, the DEPMAP portal." (PMID 37206090, 2023). "The SRSF1 gene may regulate the occurrence of EMT in cancer cells by positively regulating the expression of the transcription factor SNAIL." (PMID 38002944, 2023). "SRSF1 is upregulated in varies cancer type and controls alternative splicing of many tumor-related genes, which affect cell apoptosis, proliferation and migration thereby promoting tumorigenesis and cancer development." (PMID 36911524, 2023). "As an oncoprotein, elevated SRSF1 expression has been reported in various cancers." (PMID 36140826, 2022). "Notably, we found SRSF1, HECW2, SRSF6, UBE2Z and PCF11, to be linked to carcinogenesis and cancer management 51-62 and are associated with poor prognosis in HMs." (PMID 35711821, 2022).
cancer (continued). "SRSF1 is a critical oncoprotein overexpressed in several cancers including human NSCLC." (PMID 35027535, 2022). "Moreover, we determined that SRSF1, by modulating the pro-proliferative Kras 4B isoform, alters cancer stem cell plasticity, the invasive potential of advanced tumours and the viability of primary CRC organoids derived from patients." (PMID 35589755, 2022). "On the other hand, the roles of eIF4B and SRSF1 in cancer have been widely elucidated." (PMID 35571614, 2022). "Moreover, SRSF1 was defined as a proto-oncogene, since upregulation of SRSF1 favors the formation of a variety of cancers." (PMID 36458014, 2022). "Collectively, our results demonstrate that SRSF1 might promote cancer cell growth partially through the SRSF1/PTPMT1 splice switching AKT/C-MYC signaling axis." (PMID 33992102, 2021). "SRSF1 also correlated with poor cancer prognosis in a hormone receptor-positive (HR+) cohort." (PMID 33992102, 2021). "In agreement with the proliferative and oncogenic functions of SRSF1, the depletion of SRSF1 in healthy neurons leads to down-regulation of markers of the G1/S cell cycle transition and mitosis as well as of cell proliferation and cancer markers." (PMID 34376242, 2021). "Moreover, cardinal studies have shown that SRSF1 is upregulated in several tumors and exerts tumorigenesis roles by regulating the AS events of some cancer-related genes." (PMID 33992102, 2021). "Altogether, our data suggest that knockdown of SRSF1 could inhibit Gefitinib-resistant cancer cells progression at least in part via activating autophagy." (PMID 33664238, 2021). "To further confirm that SRSF1-knockdown could inhibit Gefitinib-resistant cancer cell progression through activation of autophagy, we knocked down ATG5, a factor required for autophagic vesicle formation, in SRSF1-reduced Gefitinib-resistant HCC827 cells." (PMID 33664238, 2021). "These compounds induced SRSF1-dependent AS by inhibiting CLK activity in cancer cells." (PMID 34065983, 2021). "While the full spectrum of SRSF1 function remains to be determined, our results reveal that SRSF1 binds to specific miRNAs and is significantly involved in exosome miRNA enrichment in cancer cells." (PMID 32819370, 2020). "Therefore, the oncogenic lncRNA NEAT1 seems to be independently stabilized by two different RBPs, by HuR and SRSF1, which are both frequently overexpressed in cancer." (PMID 32340118, 2020). "SRSF1 is an oncogenic splicing factor that is upregulated in various cancers." (PMID 32967226, 2020). "SRSF1 is also upregulated and acts as oncoprotein in several cancers." (PMID 30736462, 2019). "PTBP1 and SRSF1 are two splicing factors known to be involved in cancer." (PMID 30962446, 2019). "SRSF1 has been proposed as a proto-oncogene because it is overexpressed in many cancers." (PMID 28806747, 2017). "Alternatively, when SRSF1, 3, 5, and 7 were upregulated in whole cancer-cell lysates, they were predominantly distributed in nuclear and/or membrane/organelle fractions; the upregulated SFs in the membrane/organelle fraction were detectable in >50 % of upregulated cases in both cancers." (PMID 27282379, 2016). "SRSF1 is considered a proto-oncogene that is overexpressed in various cancers." (PMID 25658361, 2015). "SRSF1 is a proto-oncogene that is overexpressed in many different cancers." (PMID 26209438, 2015). "In addition, we resume current knowledge on deregulated SRSF1 expression in tumors and describe SRSF1-regulated alternative transcripts with functional consequences for cancer cell biology at different stages of tumor development." (PMID 26273603, 2015). "Importantly, cancer cells modulate the expression levels of SRSF1, splicing of the ΔRON isoform, and induction of EMT in response to external cues from the surrounding environment." (PMID 26273627, 2015). "The upregulation of SRSF1 in cancer could also occur through a failure of its autoregulation or through the inactivation of specific microRNAs." (PMID 24101931, 2013).
cancer (continued). "A number of the SR proteins have been found to have roles in cancer, amongst them, SRSF1 and SRSF3." (PMID 23935626, 2013). "SRPK1 overexpression has also been observed in several cancers, and so it is conceivable that its activation could also synergistically potentiate the oncogenic properties of SRSF1." (PMID 24101931, 2013). "SRSF1 upregulation in cancer cells can occur through two distinct mechanisms." (PMID 23935626, 2013). "As well as being upregulated in some cancer cells, SRSF1 operates as a bona fide oncogene." (PMID 23935626, 2013). "Firstly, the SRSF1 gene itself can become amplified in cancer." (PMID 23935626, 2013). "However, despite an increase in Mcl-lS expression when cancer cells were depleted of SRSF1 the relative levels of pro-apoptotic McL-1S compared to those of anti-apoptotic Mcl-1L remained low." (PMID 23284704, 2012). "In addition, genes whose expression was suppressed by BA included ID1, which is associated with regulation of CSCs and treatment resistance; SRSF1, which contributes to RNA splicing that alters cancer stem cell plasticity; and LIN28B, an oncogenic stem cell factor involved in EMT." (PMID 40316727, 2025). "Moreover, SRSF1 also regulates the splicing of some other cancer-related genes, such as BIM, BIN, and MCL1, which might account for that ectopic expression of Bcl-xL only partially rescues the phenotype." (PMID 33664238, 2021). "Importantly, SRSF1 is over-expressed in different cancer types and is considered a potent oncogene." (PMID 32819370, 2020). "Thus, the upregulation of SRPK1 and SRSF1 activity frequently observed in human cancers might contribute to the ability of the tumour mass to promote neoangiogenesis and redirect the blood stream towards itself." (PMID 26273627, 2015). "Consistently, the expression of mesenchymal biomarkers N-Cadherin, Vimentin and Snail and cancer stemness biomarkers USP37, ALDH1, OCT4 and Smo/Gli-1 in BC cells was suppressed by CYT and markedly recovered by SRSF1 overexpression." (PMID 40176901, 2025). "RIF1 alternative splicing was regulated by a suite of RNA-binding proteins, including serine and arginine rich splicing factor 1 (SRSF1), SRSF3, and SRSF7 whose expression and occupancy on RIF1 pre-mRNA changed in response to DNA damage and in primary cancers." (PMID 41489901, 2025). "Consistent with its role in preventing exon skipping in MYC-driven cancers, PRMT5 likely promotes SRSF1 recruitment to Tip60 pre-mRNA to support splicing of full-length, catalytically active Tip60." (PMID 40846633, 2025). "Serine/arginine-rich splicing factor 1 (SRSF1, previously SF2/ASF) is a widely studied and important splicing factor involved in cancer progression, heart development, and thymus development." (PMID 38271475, 2024). "In particular, several splicing factors, such as hnRNP A2/B1, SRSF1, and SRSF6, have been shown to act as driver oncogenes in some cancers; thus, they have gained attention as promising targets for cancer therapy." (PMID 38110955, 2023). "SRSF1 expression maintains stemness in human CRC organoids and correlates with cancer stem cell marker expression in human tumours." (PMID 35589755, 2022). "Moreover, RBPs such as SRSF1 have been shown to be a direct target of oncogenes, providing a scenario whereby oncogenic activation of these splicing factors may lead to far-reaching alterations in splicing profiles across cancer types." (PMID 35463320, 2022). "MiR-7, for example, inhibits SF SRSF1 mRNA translation in HeLa cells via partial complementarity with its 3’UTR, suppressing cancer cell survival." (PMID 36144454, 2022). "SRSF1 is involved in the expression of various cancer-promoting genes, including pro-apoptotic Bcl-x, R.O.N., and MCL-1 isoforms and activating SRSF1 through its kinase SRPK1 is activated by HPCV infection." (PMID 36144454, 2022).
cancer (continued). "Serine and arginine rich splicing factor 1 (SRSF1) is highly expressed in a variety of tumor cells and plays a role through alternative splicing of genes related to cancers." (PMID 36062189, 2022). "Relative to SRSF1 and SRSF2, much less is known about the other SR proteins and their relationship with cancer." (PMID 35463320, 2022). "Host RNA splicing factor SR proteins, including SRSF1(ASF/SF2), SRSF2 (SC35), SRSF3 (SRp20), and SRSF10 (SRp38/SRrp40), are also upregulated in HPV-positive cervical precancer lesions and cancer tissues." (PMID 35563334, 2022). "In our study, we also demonstrated that SRPK1 and SRSF1 were involved in the production of alternative splicing of VEGF-A165b in RCC cells and promoted cancer progression, which is consistent with the anti-angiogenic effect of VEGF-A165b in previous studies." (PMID 34544400, 2021). "In HeLa cells, miR-7 inhibits the mRNA translation of the SF SRSF1 through partial complementation with its 3’UTR to downregulate SRSF1-mediated AS, suppressing cancer cell survival." (PMID 33407694, 2021). "Interestingly, SRSF1 may also act as an oncogene in several cancers." (PMID 34769047, 2021). "With our current results of FOXP3-mediated ATF3 regulation, future studies are indeed necessary to explore the FOXP3 spliced isoforms in ATF3 regulation as well as the role of SRSF1 in FOXP3 isoform regulation, especially in the cancer field." (PMID 34768829, 2021). "Whereas overexpression of SRSF1 led to a substantially decreased accumulation of LC3-II and autophagosomes amount in several cancer cell lines." (PMID 33664238, 2021). "Mutation, misexpression or mislocalization of RNA binding proteins SRSF1, hnRNPs, or RBM regulating splicing have been reported in several cancers." (PMID 31683936, 2019). "Relevant to this, we demonstrate that inhibition of the oncogenic splicing factors SRSF1 and PTBP1 inhibits the oncogenic properties of cancer cells." (PMID 30962446, 2019). "Still, reduced expression of SRSF1 and SRSF2 proteins in the cancer cells weakly correlated with signature of mirtronic miRNA expression." (PMID 27019673, 2016). "Second, the SRSF1 gene is a target of MYC, a potent oncogenic transcription factor overexpressed in many different tumor types that has pleiotropic effects on cancer cell biology." (PMID 26273603, 2015). "The splicing regulator proteins SRSF1 (also known as ASF/SF2) and SRSF3 (also known as SRP20) belong to the SR family of proteins and can be upregulated in cancer." (PMID 23935626, 2013). "We have shown that SRSF1 (a member of the SR family also known as SF2/ASF) can regulate the epithelial-to-mesenchymal transition (EMT) and the migratory properties of cancer cells." (PMID 23863836, 2013). "Similarly, the levels of SRSF1 and the other SR proteins are thought to be normally autoregulated through poison exon inclusion; so these other SR proteins must similarly bypass these mechanisms in cancer cells to enable their higher levels of expression to be established." (PMID 23935626, 2013). "The application of the ESTIMATE algorithm revealed a positive correlation between SRSF1 mRNA expression and exhausted CD8+ T cells across various cancers, but negative correlation can be seen between SRSF1 mRNA and cytotoxic or memory T cells." (PMID 39837814, 2025). "We conducted scRNA-seq on four HCC tissues—two responsive and two non-responsive—to investigate SRSF1 expression in CD8+ T cells during neoadjuvant anti-PD-1 cancer immunotherapy." (PMID 39837814, 2025). "SRSF1, acting as a direct target of PRMT5, plays a crucial role in promoting cancer in AML." (PMID 38302461, 2024). "Lower levels of exosomal circSMARCA5 can inhibit the migration of GBM cells through the regulation of the SRSF1/SRSF3/PTB axis, indicating that it may function as a potent tumor suppressor in this cancer type through the inhibition of SRSF1 function." (PMID 37122733, 2023).
cancer (continued). "While SRSF1 is well-studied in the context of cancer and cardiac physiology, its function in the liver is not well understood." (PMID 36759613, 2023). "SRSF1 has also been found to regulate the expression of two isoforms of the MAPK pathway component MNK2—MNK2a and MNK2b—while the MAPK pathway mediates EMT in cancer." (PMID 38002944, 2023). "MYC is an essential molecular hub in CML pathophysiology and could actively participate in the dysregulation of PTBP1 and hnRNPA1 as well as PRMT5 and SRSF1, genes deregulated by MYC in other cancers." (PMID 36230624, 2022). "Therefore, examining the splicing regulation of the splicing factor SRSF1 by USP15 and USP4 in cancer progression was our particular interest." (PMID 35027535, 2022). "Next, we examined whether the cancer progression ability of USP15 and USP4 is allied with SRSF1 alternative splicing." (PMID 35027535, 2022). "Among the 20 tumor tissues, 13 cases (65%) showed high expression of SRSF1, whose expression rate was significantly higher than that of ESCC adjacent tissues (P < 0.01), confirming SRSF1 was considered as a potential cancer-related gene in ESCC." (PMID 34099633, 2021). "Moreover, the circRNA circSMARCA5 binds and decoys the SF SRSF1 away from VEGF-Axxxa pre-mRNA to decrease the expression of the proangiogenic splicing isoform VEGF-Axxxa, repressing cancer progression in glioblastoma multiforme." (PMID 33407694, 2021). "SRSF1, along with SF3B1, are also involved in apoptosis modulation in cancer through AS." (PMID 34356101, 2021). "Several SR proteins, such as SRSF1, SRSF3, and SRSF6, are also amplified in multiple cancer types." (PMID 32481522, 2020). "Along with the increased level of SRSF1 (with which HABP1/p32 was initially purified), colocalization with HABP1 and localization of SRSF1 in the nuclear speckles gives fuel to the proposition of the involvement of HABP1 in cancer progression." (PMID 29535843, 2018). "Upregulated SRSF1 expression mediates a switch in the splicing profiles of BIN1 and CASP9 to generate pro-oncogenic isoforms which interfere with the apoptosis of diverse cancer cells." (PMID 29283381, 2017). "Whilst acute VEGF‐B induced phosphorylation of SRSF1, a splice factor that is often associated with VEGF‐A splicing in podocytes and in cancer cells 18, no changes in total VEGF‐A or VEGF‐A165b were observed." (PMID 26957058, 2016). "Finally, we found that overexpression of well-known splicing factors SRSF1 and SRSF2 increased the abundance of some mirtron-derived miRNAs in colorectal HCT116 cancer cells." (PMID 27019673, 2016). "Accordingly, tumor-promoting roles of SRSF1 and SRSF2 have been reported in various cancer types." (PMID 27019673, 2016). "By understanding the molecular mechanisms regulating MDM2 splicing in response to damage and potentially in cancer we have paved the way for the development of novel splice modulation strategies for adjusting MDM2 levels in cancers with elevated MDM2-ALT1 and SRSF1 expression." (PMID 25845590, 2015). "Among these, only IDC92 is able to revert the invasive phenotype of cancer cells without affecting the splicing profile of other SRSF1 targets, suggesting that this small molecule is suitable for further in vivo studies." (PMID 24285959, 2013). "Both SRSF1 and PRMT1 were over-expressed in ND samples, and were reduced to normal levels upon CR, which is supported by reports that SRSF1 and PRMT1 are highly expressed in many cancers." (PMID 22839530, 2012). "However, when specific to certain cancer types or genes, this negative correlation did not hold, such as SRSF1 in LUSC and KICH; SRSF4 in TGCT, and SRSF5 in LAML and MESO (p < 0.05)." (PMID 38015716, 2023). "Altogether our data address SRSF1 as a critical modulator of endogenous MDM2 alternative splicing, providing necessary information in the regulation of this important oncogene and a potential therapeutic target for intervention in the myriad cancers in which MDM2-ALT1 is observed." (PMID 25845590, 2015).